STX6 (syntaxin 6)
Diseases named in the same sentence as STX6 in open-access papers (continued):
Sharing a sentence is not in itself a finding about the gene and the disease.
cancer (9 papers, 2012 to 2024). A tumor composed of atypical neoplastic, often pleomorphic cells that invade other tissues. "GSEA was used to identify STX6-associated cancer hallmarks by comparing gene expression differences between low-STX6 and high-STX6 subgroups in each malignancy." (PMID 36612024, 2022). "We investigated the STX6 alteration frequency and mutation count in cancer patients using the cBioPortal database." (PMID 36612024, 2022). "The findings show that, in 29 different types of cancer, STX6 mRNA expressions were mostly positively linked with CNV." (PMID 36612024, 2022). "On the other hand, a negative association existed between STX6 and these parameters in OV, which suggests that STX6 is a more likely risk factor for patients who have cancer." (PMID 36612024, 2022). "In this work, we discovered that the expression level of STX6 was inversely linked with the amount of promoter methylation in 25 types of cancer we examined." (PMID 36612024, 2022). "In our work, we utilized a systematic pan-cancer analysis and in vitro and in vivo experiments to determine that STX6 expression is increased in most cancers and may be used as an independent risk factor to anticipate patient survival." (PMID 36612024, 2022). "We next thoroughly explored the biological importance of STX6 in cancer hallmark gene sets." (PMID 36612024, 2022). "STX6 mRNA expression levels were examined between tumor and surrounding normal tissues in 32 cancer types using data from TCGA and GTEx." (PMID 36612024, 2022). "STX6 was strongly related to the survival probability of a total of 14 cancer types, as shown by the Kaplan–Meier curves." (PMID 36612024, 2022). "In light of the essential roles STX6 plays in carcinogenesis and cancer immunology, it has the potential to be a predictive biomarker and a target for cancer immunotherapy." (PMID 36612024, 2022). "RNA-seq indicated that STX6 was significantly involved in pathways for cancer, such as the MAPK signal pathway." (PMID 36612024, 2022). "Recent studies have demonstrated the carcinogenic role of STX6 in many types of cancer, including cervical cancer, renal cell carcinoma, and pancreatic ductal adenocarcinoma." (PMID 36612024, 2022). "In this research, we comprehensively explored the role of the oncogene STX6 in pan-cancer by combining data from several databases, including the Cancer Genome Atlas, CPTAC, cBioPortal, and TIMER." (PMID 36612024, 2022). "To further evaluate STX6’s critical involvement in carcinogenesis and progression, we established a xenograft cancer model by injecting CT26 cells expressing varying quantities of STX6 into Balb/c mice." (PMID 36612024, 2022). "Using several cancer cell models, mislocalization of the SNARE protein Stx6 was identified as an underlying cause." (PMID 35806209, 2022). "There was an increase in the mRNA expression of STX6 in tumor tissues compared to neighboring normal tissues in all cancers." (PMID 36612024, 2022). "Cancer-associated fibroblasts and endothelial cells are tightly associated with the TGF BETA and VEGF signaling pathways, indicating that STX6 is likely implicated in the tumor microenvironment and cancer metastasis." (PMID 36612024, 2022). "To explore its biological function and mechanism, we established the STX6 knockdown cancer cell lines BEL-7404 and HCT-116 by lentivirus transfection." (PMID 36612024, 2022). "STX6 is a reliable biomarker for predicting the prognosis of patients with cancer and the effectiveness of immunotherapy." (PMID 36612024, 2022). "Combining clinical parameters with STX6 expression led to the development of a nomogram that accurately predicts the prognosis of cancer patients." (PMID 36612024, 2022). "STX6’s predictive relevance in malignancies drove us to further study STX6-detrimental and STX6-favorable cancer subtypes." (PMID 36612024, 2022).
cancer (continued). "High syntaxin 6 expression has also been reported in numerous cancers including breast, colon, liver, pancreatic, prostate, bladder, skin, testicular, tongue, cervical, lung and gastric cancers." (PMID 30816681, 2019). "Gene expression analyses have demonstrated that syntaxin 6 is upregulated in numerous cancers including breast, colon, liver, pancreatic, prostate, bladder, skin, testicular, tongue, cervical, lung and gastric cancers." (PMID 30816681, 2019). "Furthermore, endothelial cells had a favorable correlation with STX6 in most cancers (18 of 40 cancer types)." (PMID 36612024, 2022). "Many studies have highlighted STX6 as a possible therapeutic target in cancer." (PMID 36612024, 2022). "Bioinformatics analysis demonstrated that STX6 is an oncogene for several cancers and is mainly involved in the cell cycle, epithelial–mesenchymal transition, oxidative phosphorylation, and tumor immune modulation, especially for tumor-associated fibroblasts (CAFs) and NKT cells." (PMID 36612024, 2022). "Furthermore, in the association study between STX6 and copy number variation (CNV), another indication demonstrates the deletion or amplification of genomic DNA in the full chromosomal set of cancer and genetic illnesses." (PMID 36612024, 2022). "In this research, we comprehensively analyzed the carcinogenic role of STX6 in pan-cancer, and we found that STX6 may also play an essential role in the tumor microenvironment, and that knocking down STX6 could enhance the effect of anti-PD-1." (PMID 36612024, 2022). "In this study, we comprehensively analyzed the carcinogenic role of STX6 in pan-cancer and explored whether it also plays an important role in the tumor microenvironment." (PMID 36612024, 2022). "Furthermore, the migration and invasion abilities of cancer cells were weakened when the STX6 level was decreased." (PMID 36612024, 2022). "The results showed that STX6 was significantly negatively correlated with NKT cells in pan-cancer, which suggests that STX6 may help immune escape by stopping the expression of NKT cells." (PMID 36612024, 2022). "These Stx6- and LE/Lys-Chol-dependent events relevant for cancer cell motility might require cooperation with Rab11, which also stimulates β1 integrin recycling, and influences cholesterol homeostasis in recycling endosomes." (PMID 35806209, 2022). "Thus, elevated Stx6 levels in breast, liver and prostate cancers might reflect the need for cancer cells to establish fast and efficient transport that accommodates and couples higher cholesterol fluxes with integrin recycling kinetics." (PMID 35806209, 2022). "In addition, as a vesicle transport protein, STX6 can participate not only in the regulation of the size and number of extracellular vesicles, but also in the efflux of cancer cells to chemotherapy drugs through the form of vesicle transport to promote cell resistance to chemotherapy." (PMID 36612024, 2022). "Some of the prominent genes we identified through the networks are DOK5, APP, CTNND1, STX6, STX10, STX16, BACE1, and BACE2; which, agree with the regulation of various cancers based on their co-expression patterns in GeneMANIA." (PMID 37218885, 2023). "The findings revealed that STX6 was favorably related to the cell cycle, MAPK signaling pathway, TGF BETA signaling pathway, VEGF signaling circuit, and cancer pathways in ACC, KIRP, LIHC, or PAAD, but OV showed the contrary." (PMID 36612024, 2022). "STX6 protein expression was elevated in the HCC and CRC cancer cell lines." (PMID 36612024, 2022). "The link between STX6 expression and TMB gained significance (p < 0.05) in eight types of cancer." (PMID 36612024, 2022).
cancer (continued). "As expected, the STX6 staining score in tumor tissues was higher than that in normal tissues in all cancer types included in the study." (PMID 36612024, 2022). "Additionally, we discovered that the expression of STX6 showed a favorable link with READ, LAML, COAD, LUSC, and UCEC, but a negative relationship with the MSI of five different cancers, including DLBC, LGG, HNSC, THCA, and SKCM." (PMID 36612024, 2022).
tumor (8 papers, 2019 to 2025). "Multivariate Cox regression analysis identified SNPs in 8 genes (Stx6, Ramp1, Traf3ip1, Nckap5, Pfkfb2, Trmt1l, Rprd1b, and Rer1) that were independently associated with age of tumour onset." (PMID 39067134, 2024). "Multivariate linear regression analysis identified SNPs in 11 genes (Sepsecs, Rhobtb1, Tsen15, Abcc3, Arid5b, Tnr, Dock2, Tti1, Fam81a, Stx6, and Oxr1) that were independently associated with the tumour multiplicities." (PMID 39067134, 2024). "In ESCC, a previous report showed that STX6 was upregulated and significantly associated with tumor size, histologic differentiation, lymph node involvement, and the extent of tumor invasion; in addition, STX6 activity was associated with ESCC progression." (PMID 38014487, 2023). "STX6 was primarily implicated in tumor growth through the microRNA, MAPK, and TNF signaling pathways." (PMID 36612024, 2022). "Herein, we explored the associations between STX6 expression and tumor microenvironment makeup by adopting the ESTIMATE method to compute the immune and stromal scores." (PMID 36612024, 2022). "We pooled all 20 genes (Stx6, Ramp1, Traf3ip1, Nckap5, Pfkfb2, Trmt1l, Rprd1b, Rer1, Sepsecs, Rhobtb1, Tsen15, Abcc3, Arid5b, Tnr, Dock2, Tti1, Fam81a, Oxr1, Plxna2 and Tbc1d31) together as the mouse tumour susceptibility gene signature (mTSGS)." (PMID 39067134, 2024). "We anticipated that tumor-associated fibroblasts and vascular endothelial cells might be closely connected to STX6 based on the KEGG findings for STX6 in malignancies." (PMID 36612024, 2022). "Mechanistically, STX6 mediated tumor progression depending on promoting the activation of JAK-STAT signaling pathway." (PMID 38834986, 2024). "Consistent with our in vitro results, the tumor size and weight of nude mice overexpressing STX6 were significantly larger than those of the control group." (PMID 37564208, 2023). "We then verified the expression of STX6 in xenografted tumor tissues by qRT-PCR and western blot assays and found that STX6 expression in MHCC-97h cells was lower than that in the control group whereas that in Huh7 cells was higher." (PMID 37564208, 2023). "Collectively, our study demonstrated for the first time the tumor-promoting role of STX6 in HCC and confirmed that high STX6 expression promoted HCC proliferation and metastasis in vivo and vitro and promoted autophagic flux in HCC cells." (PMID 37564208, 2023). "Analyses of removed tumors using immunofluorescence (immunohistochemistry) revealed that STX6 knockdown significantly increases the infiltration level of CD8α in the tumor microenvironment." (PMID 36612024, 2022). "To further corroborate the data provided by our bioinformatics, we conducted immunohistochemical analysis to evaluate the protein levels of STX6 in tumor and normal tissues in common tumor types, including THCA, ESCA, STAD, COAD, PAAD, LUSC, and KRC." (PMID 36612024, 2022). "Syntaxin 6 induced tumour progression through an adaptor, RACK1, which recruited STAT3." (PMID 40293576, 2025). "In a mouse model, knockdown of STX6 inhibited tumor growth and potentiated anti-PD-1 efficacy." (PMID 36612024, 2022). "In summary, our work discovered that STX6 may control T-cell infiltration in the tumor microenvironment, and that it has an oncogenic function in a number of malignancies." (PMID 36612024, 2022). "By encouraging cell-cycle progression, cell metastasis, and treatment resistance, STX6 may facilitate tumor progression." (PMID 36612024, 2022). "Multivariate analyses flagged SNPs in 20 genes (Stx6, Ramp1, Traf3ip1, Nckap5, Pfkfb2, Trmt1l, Rprd1b, Rer1, Sepsecs, Rhobtb1, Tsen15, Abcc3, Arid5b, Tnr, Dock2, Tti1, Fam81a, Oxr1, Plxna2, and Tbc1d31) independently tied to various tumour characteristics, designated as a mTSGS." (PMID 39067134, 2024). "However, STX6’s function in the tumor microenvironment has yet to be reported." (PMID 36612024, 2022).
tumor (continued). "Furthermore, STX6 expression was favorably connected to the mitotic spindle, G2M checkpoint, and epithelial–mesenchymal transition, demonstrating that STX6 was strongly related to tumor proliferation and metastasis." (PMID 36612024, 2022). "Moreover, we discovered that STX6 might enhance tumor growth via involvement in CAFs and T-cell infiltration in the tumor microenvironment." (PMID 36612024, 2022). "In addition, STX6 may have a role in a number of other biological processes that contribute to tumor development and progression." (PMID 36612024, 2022). "Therefore, STX6 may also play an essential role in the tumor microenvironment." (PMID 36612024, 2022). "Other studies reported the axis of syntaxin 6/USF2/LC3B which promoted autophagy flux and tumour progression in HCC, showing that syntaxin 6 could trigger autophagy and affect the RACK1/STAT3 axis." (PMID 40293576, 2025). "Collectively, these results showed that STX6 promoted HCC tumorigenicity and tumor tissue growth." (PMID 37564208, 2023). "Conversely, tumor size was significantly reduced in the STX6 knockdown group compared to that in the negative control group." (PMID 37564208, 2023). "Lastly, this work did not investigate the precise method via which STX6 is involved in the tumor microenvironment." (PMID 36612024, 2022). "Previous studies have proven that STX6-mediated intracellular transport of vascular endothelial growth factor 2 (VEGFR2), epidermal growth factor receptor (EGFR), and integrins regulates tumor proliferation, angiogenesis, and metastasis." (PMID 36612024, 2022). "To validate this result, we performed quantitative real-time PCR assays (RT-PCR) and western blot assays using tumor and matched noncancerous tissues obtained from patients with HCC to detect the expression of STX6." (PMID 37564208, 2023).
neurodegenerative disease (5 papers, 2017 to 2026). A disorder of the central nervous system characterized by gradual and progressive loss of neural tissue and neurologic function. "This work strengthens the case for syntaxin-6 as a pleiotropic risk factor in neurodegenerative disease, anchored in human genetics, and sheds light on the specific stage of disease at which it acts." (PMID 41186731, 2025). "Syntaxin-6 appears to have pleiotropic risk effects across multiple neurodegenerative diseases including PSP and AD." (PMID 37996040, 2024). "Thus, this work supports further exploration of the STX6 susceptibility mechanism, which likely has relevance across multiple neurodegenerative diseases." (PMID 37996040, 2024). "Finally, the pleiotropic role of syntaxin-6 across multiple neurodegenerative diseases, including PSP and AD, raises the potential that STX6-targeting therapies could have wider applicability to other neurode-generative diseases, warranting further investigation." (PMID 37996040, 2024).
infection (4 papers, 2021 to 2025). The state of being infected such as from the introduction of a foreign agent such as serum, vaccine, antigenic substance or organism. "To ascertain whether STX6 limits the infection of various SARS-CoV-2 variants, we conducted further experiments to assess the impact of STX6 knockdown and overexpression on SARS-CoV-2 delta and Omicron BA.2, BA.5, and XBB.1.9 strains." (PMID 40277356, 2025). "Furthermore, when we challenged PK1 Stx6 knockdown cell lines with a limiting dose of prions, cells became susceptible to prions, in contrast to controls which were resistant to infection." (PMID 41186731, 2025). "Given that STX6 colocalized with SARS-CoV-2 particles shortly after infection, we proceeded to analyze the impact of STX6 on the entry efficiency of SARS-CoV-2 spike pseudovirus." (PMID 40277356, 2025). "Given our observation of the colocalization of endogenous STX6 with SARS-CoV-2 S and N protein shortly after infection, we proceeded to investigate the subcellular localization of STX6." (PMID 40277356, 2025). "Strengthening these findings, infection of PK1 Stx6 overexpression cell lines resulted in a robust reduction in the spot count, suggesting that overexpression may enhance clearance of prion infection." (PMID 41186731, 2025). "Consistent with previous findings that VSV-G and HCV envelope proteins may initiate autophagy, and EV71 can trigger autophagy by pore formation, our results suggest a restriction role of STX6 in these viruses’ infection." (PMID 40277356, 2025). "Neither the spike protein nor ACE2 could be co-immunoprecipitated with STX6, whereas colocalization of endogenous STX6 with SARS-CoV-2 spike and N protein was observed 1 h post-infection, suggesting the proximity of STX6 to endocytic viral particles." (PMID 40277356, 2025). "Confocal imaging of infected Stx6 overexpression cells revealed a universal reduction in 6D11 and 5B2 staining, suggesting that syntaxin-6 overexpression was sufficient to almost clear the infection, corroborating the SCA data." (PMID 41186731, 2025). "However, the colocalization of pseudovirus with Rab7 was markedly elevated in STX6 knockdown cells at both 30 and 90 min post-infection, whereas its colocalization with LAMP1 was modestly reduced at the same time points." (PMID 40277356, 2025). "Initially, we demonstrated that the cells transduced with S-EGFP pseudovirus exhibited distinct EGFP signals in punctate patterns shortly after an infection, and these EGFP signals colocalized with endogenous STX6, a finding consistent with that observed with the authentic virus." (PMID 40277356, 2025). "Despite observing profound phenotypic differences in chronically infected cells with syntaxin-6 knockdown, there were no changes in total prion load during established infection, in line with the in vivo results where we only found effects of syntaxin-6 manipulation on disease risk." (PMID 41186731, 2025). "Although we found no consistent effect in Stx6-overexpressing CAD5 cells, knockdown in CAD5 cells consistently increased the spot count after RML infection, corroborating the PK1 data." (PMID 41186731, 2025).
movement disorder (1 paper, 2025). Neurological conditions resulting in abnormal voluntary or involuntary movement, which may impact the speed, fluency, quality and ease of movement. "Rescued XDP signature genes such as GABRA5, STX6, and ATP6V0A1 code for subunits of channels or receptors that map to glutamatergic or GABAergic synapses, cellular components that are relevant for neurotransmission and the movement disorder phenotype observed in XDP." (PMID 41282719, 2025).
STX6 also shares sentences with these, for which no sentence is quoted: frontotemporal Lobar degeneration (2 papers); papillary renal cell carcinoma (2); sporadic Creutzfeldt-Jakob disease (2); amyotrophic lateral sclerosis (1); bacterial infection (1); breast tumors (1); Burkitt lymphoma (1); cardiac arrhythmia (1); cervical cancer (1); cholangiocarcinoma (1); colorectal cancer (1); Creutzfeldt-Jakob disease (1); glioblastoma (1); head and neck cancer (1); kidney cancer (1); leishmaniasis (1); leukemia (1); lung carcinoma (1); macrosomia (1); microcephaly (1); neuroblastoma (1); neurologic disease (1); osteosarcoma (1); Pan (1); pancreatic cancer (1); pancreatic ductal adenocarcinoma (1); small cell lung carcinoma (1).